RASGEF1A (RasGEF domain family member 1A)
Description:
Guanine nucleotide exchange factor (GEF) with specificity for RAP2A, KRAS, HRAS, and NRAS (in vitro). Plays a role in cell migration.
Synonyms: CG4853; FLJ37817
Tractability: Antibody: its Gene Ontology location is reachable by antibodies, with medium confidence.
Gene: Protein-coding gene on chromosome 10 (43,194,533 to 43,267,082, reverse strand). Ensembl gene ENSG00000198915.
Subcellular location (Human Protein Atlas): Golgi apparatus
Pathways (Reactome):
Signal Transduction: RAF/MAP kinase cascade
Gene Ontology:
Molecular function: guanyl-nucleotide exchange factor activity
Biological process: cell migration; positive regulation of Ras protein signal transduction; Ras protein signal transduction; small GTPase-mediated signal transduction
Cellular component: cytosol; plasma membrane
Genetic constraint (gnomAD): Loss-of-function variants: 18 observed, 53.2 expected, observed/expected ratio (o/e) 0.34, 90% interval 0.23 to 0.5. The upper end of that interval is the gene's LOEUF score, 0.5, which puts it in group 2 of 6, group 1 being the genes least tolerant of losing a copy. Missense variants: 422 observed, 623.11 expected, observed/expected ratio (o/e) 0.68, 90% interval 0.62 to 0.73. Synonymous variants: 245 observed, 243.27 expected, observed/expected ratio (o/e) 1.01, 90% interval 0.91 to 1.12.
Homologues: Orthologues: chimpanzee RASGEF1A (99% identical), macaque RASGEF1A (99% identical), pig RASGEF1A (96% identical), dog RASGEF1A (94% identical), mouse Rasgef1a (94% identical), guinea pig RASGEF1A (94% identical), rat Rasgef1a (93% identical), tropical clawed frog rasgef1a (77% identical). Paralogues in human: RASGEF1B (59% identical), RASGEF1C (53% identical), RAPGEF3 (22% identical), RALGDS (21% identical), RAPGEF2 (21% identical), RASGRF1 (21% identical), RAPGEF6 (21% identical), RASGRF2 (20% identical), RAPGEF1 (20% identical), RAPGEF5 (20% identical), RAPGEF4 (19% identical), RGL1 (19% identical), and 12 more.
Diseases named in the same sentence as RASGEF1A in open-access papers:
RASGEF1A is named in the same sentence as 6 diseases in open-access papers, as found by Europe PMC text mining. Sharing a sentence is not in itself a finding about the gene and the disease. The quoted sentences say what the papers report.
breast carcinoma (3 papers, 2015 to 2024). "In conclusion, we performed the first isoform-level transcriptome analysis of PBMCs from breast cancer (BC) patients and identified the ENST00000374459 RASGEF1A isoform as BC-associated." (PMID 39335143, 2024). "The novel RASGEF1A-RET fusion was detected in an ER−/PR−/HER2− breast cancer and results from an inversion event on chromosome 10 with breakpoints in RASGEF1A intron 1 and RET intron 9 that juxtaposes the 5′UTR of RASGEF1A upstream of the RET kinase domain." (PMID 30446652, 2018). "In breast cancer, it is possible that the observed downregulation of the 374459 RASGEF1A isoform in PBMCs of BC patients may affect the activity of these immune cells." (PMID 39335143, 2024). "Based on initial detection in two index cases with RET fusions (RASGEF1A-RET and NCOA4-RET), 9693 breast cancers were evaluated for the presence of RET rearrangements as well as missense mutations and copy number changes." (PMID 30446652, 2018).
cholangiocarcinoma (1 paper, 2016). A carcinoma that arises from the intrahepatic biliary tree (intrahepatic cholangiocarcinoma) or from the junction, or adjacent to the junction, of the right and left hepatic ducts (hilar cholangiocarcinoma). "Overexpression of RASGEF1a, an activator of the RAS family of oncogenes promoting cellular migration, is linked to oncogenesis in cholangiocarcinoma." (PMID 26981160, 2016).
cancer (6 papers, 2012 to 2025). A tumor composed of atypical neoplastic, often pleomorphic cells that invade other tissues. "Based on a previous study on RASGEF1A, RASGEF1A may be able to increase the activity of the Ras signaling pathway, which promotes the growth and progression of cancer cells." (PMID 39773749, 2025). "A total of 10 genes that were disrupted or within breakpoint‐associated TAD structures were classified as known (FHIT, FLCN, NCOA4, and RET) or candidate cancer genes (LLGL1, LRIG1, LYRM9, RASGEF1A, ST3GAL6, and TMEM199)." (PMID 31943436, 2020). "In addition, expression of Kruppel-like factor 4 (KLF4), Ras guanyl nucleotide exchange factor 1A (RASGEF1A), and polo-like kinase 2 (PLK2) have been reported to exhibit anti-apoptotic and growth-promoting activity in human cancer cells and are also up-regulated by RASSF1C over-expression." (PMID 22591718, 2012).
tumor (2 papers, 2024 to 2025). "In our study, those BC patients who exhibited the highest Ki-67 values (>50%) had the lowest 374459 expression, suggesting an association between tumor proliferation and the 374459 RASGEF1A isoform." (PMID 39335143, 2024). "Therefore, in this study, we believe that in ARID1A-deficient tumor cells, nPD-L1 is signaled to activate RASGEF1A and the Ras signaling pathway, ultimately leading to resistance to Osimertinib." (PMID 39773749, 2025).
RASGEF1A also shares sentences with these, for which no sentence is quoted: aneurysm (1 paper); breast tumor (1).